GAA (alpha glucosidase)
Diseases named in the same sentence as GAA in open-access papers (continued):
Sharing a sentence is not in itself a finding about the gene and the disease.
Pompe disease (continued). "Pompe disease is a storage disorder with a partial or complete deficiency of acid a-glucosidase (GAA)." (PMID 33072949, 2018). "Another example of exon inclusion worth mentioning is the approach applied to Pompe disease, (glycogen storage disease type II) which is an autosomal recessive metabolic disorder caused by mutations in the acid α-glucosidase gene (GAA)." (PMID 28134780, 2017). "Pompe disease is caused by an inborn defect of lysosomal acid α-glucosidase (GAA) and is characterized by lysosomal glycogen accumulation primarily in the skeletal muscle and heart." (PMID 29044175, 2017). "Pompe disease is caused by mutations in lysosomal acid α-glucosidase (GAA) and patients are being treated with recombinant human α-glucosidase (rhGAA)." (PMID 29061980, 2017). "Pompe disease is a lysosomal storage disorder caused by acid-α-glucosidase (GAA) deficiency, leading to glycogen storage." (PMID 28874182, 2017). "The activity of GAA, the causative enzyme of Pompe disease, was much lower in Pom iPSCMyoD than in Ctr." (PMID 29044175, 2017). "Pompe disease is a rare autosomal recessive disorder caused by a deficiency of the lysosomal enzyme alpha-glucosidase responsible for degrading glycogen." (PMID 26471939, 2015). "In 1963, Henri Hers identified GAA as the enzyme that is deficient in Pompe patients and therefore responsible for Pompe disease." (PMID 26471939, 2015). "Pompe disease is a result of mutations in the GAA gene, which is located on the long arm of chromosome 17 (17q25.2-q25.3) and encodes the 105-kDa GAA enzyme." (PMID 26471939, 2015). "Pompe disease (OMIM 232300: acid maltase deficiency or glycogen storage disease type II) is an inherited progressive metabolic myopathy caused by acid α-glucosidase deficiency due to mutations in the acid α-glucosidase (GAA) gene (OMIM 606800)." (PMID 25943437, 2015). "Pompe disease, an inherited deficiency of lysosomal acid alpha-glucosidase (GAA), is a metabolic myopathy with heterogeneous clinical presentations." (PMID 24383498, 2014). "Pompe disease is an autosomal recessive disorder caused by a deficiency of acid α-glucosidase (GAA; EC 3.2.1.20) and the resultant progressive lysosomal accumulation of glycogen in skeletal and cardiac muscles." (PMID 25350581, 2014). "Mutations in the GAA gene that lead to a reduction in the amount or activity of the enzyme are the molecular basis of Pompe disease (glycogen storage disease type II)." (PMID 25350581, 2014). "Pompe disease is a monogenic autosomal recessive disorder caused by mutations in the acid alpha glucosidase gene (GAA, OMIM 606800), which is the only gene associated to the phenotype." (PMID 25103075, 2014). "Pompe disease is an inherited lysosomal storage disorder that results from a deficiency in acid α-glucosidase (GAA) activity due to mutations in the GAA gene." (PMID 25036864, 2014). "Pompe’s disease is a progressive myopathy caused by mutations in the lysosomal enzyme acid alphaglucosidase gene (GAA)." (PMID 25103075, 2014). "Pompe's disease is an inherited autosomal recessive disorder caused by a deficiency of the lysosomal enzyme acid alpha-glucosidase (GAA)." (PMID 25093132, 2014). "Human GAA mutations cause glycogen storage disease type II (Pompe's disease), manifestated by muscular dystrophy." (PMID 23342162, 2013). "Pompe disease is an autosomal recessive disorder in humans caused by mutations in the GAA gene (OMIM #232300,)." (PMID 23457621, 2013). "Pompe disease, also known as glycogen storage disease (GSD) type II, is caused by deficiency of lysosomal acid α-glucosidase (GAA)." (PMID 23457523, 2013). "Pompe disease (glycogen storage disease type II, acid maltase deficiency) is a rare metabolic myopathy caused by a deficiency of lysosomal acid α-glucosidase (GAA), resulting in the intralysosomal accumulation of glycogen." (PMID 23531252, 2013).
Pompe disease (continued). "In the present study we show that a recessively inherited nonsense mutation in the acid α-glucosidase (GAA) gene causes Pompe disease in both Swedish and Finnish Lapphunds as it does in humans." (PMID 23457621, 2013). "This work report the largest informative family with late-onset Pompe disease described in the literature showing a peculiar complex set of mutations of GAA gene that partially elucidate the clinical heterogeneity of this family." (PMID 24107549, 2013). "Pompe Disease (PD) (OMIM 232300, glycogen storage disease type II, acid maltase deficiency) is a rare metabolic myopathy, due to the deficiency of the lysosomal acid-α-glucosidase (GAA) (E.C. 3.2.1.20)." (PMID 23668440, 2013). "Pompe disease is a recessively inherited and often fatal disorder caused by the deficiency of acid α-glucosidase, an enzyme encoded by the GAA gene and needed to break down glycogen in lysosomes." (PMID 23457621, 2013). "Pompe disease is an inherited lysosomal storage disease that results from a deficiency in the enzyme acid α-glucosidase (GAA), and is characterized by progressive accumulation of lysosomal glycogen primarily in heart and skeletal muscles." (PMID 22815812, 2012). "Conversion from fast glycolytic to slow oxidative fibers seemed a promising therapeutic approach in Pompe disease, a severe myopathy caused by deficiency of the lysosomal enzyme acid alpha-glucosidase (GAA) which is responsible for the degradation of glycogen." (PMID 21179212, 2010). "Glycogen storage disease type II (MIM #232300), also known as Pompe disease (PD), is a rare autosomal recessive inherited metabolic disorder caused by a deficiency of lysosomal acid α-1,4-glucosidase (GAA, EC 3.2.1.20), encoded by the GAA gene." (PMID 40870023, 2025). "Pompe disease (PD) is a progressive myopathy caused by the aberrant accumulation of glycogen in skeletal and cardiac muscle resulting from the deficiency of the enzyme acid alpha‐glucosidase (GAA)." (PMID 40268518, 2025). "Background/Objectives: Pompe disease (PD) is a rare autosomal recessive disorder caused by a deficiency of the lysosomal acid α-1,4-glucosidase (GAA) encoded by the GAA gene, leading to muscular dysfunctions due to pathological accumulation of glycogen in skeletal and cardiac muscles." (PMID 40870023, 2025). "Pompe disease, also known as glycogen storage disease type II, is an inherited metabolic disorder in which a deficiency of the lysosomal enzyme acid α-glucosidase (GAA) leads to accumulations of glycogen in various tissues." (PMID 39288112, 2024). "Pompe disease is a neuromuscular disease due to a deficiency of the lysosomal enzyme GAA." (PMID 38543765, 2024). "Pompe disease, classified as glycogen storage disease type II, is an infrequent metabolic disorder resulting from a deficiency of the lysosomal acid alpha-glucosidase (GAA) enzyme." (PMID 38500078, 2024). "Pompe disease, or glycogen storage disease type II, is a lysosomal storage disorder and a metabolic myopathy caused by deficiency of lysosomal acid alpha-glucosidase (GAA, also referred to as acid maltase)." (PMID 39482698, 2024). "Glycogen storage disease type II (Pompe disease: PD) is an autosomal recessively inherited fatal genetic disorder that results from the deficiency of a glycogen hydrolyzing enzyme, acid α-glucosidase encoded by the GAA gene." (PMID 37106898, 2023). "Pompe disease, a debilitating neuromuscular illness affecting infants, children, and adults with different severity, is caused by a deficiency of lysosomal glycogen-degrading enzyme acid α-glucosidase (GAA)." (PMID 37463048, 2023). "Pompe disease (PD) is a rare, inheritable, multisystemic lysosomal storage disorder caused by a deficiency of acid alpha-glucosidase (GAA), which leads to accumulation of glycogen within lysosomes, especially in the heart, skeletal and smooth muscles, and in the nervous system." (PMID 33851281, 2022).
Pompe disease (continued). "Glycogen storage disease type II (Pompe disease or acid maltase deficiency) is an autosomal recessive metabolic disorder characterized by the accumulation of glycogen in the lysosomes due to a deficiency of the lysosomal acid alpha-glucosidase (GAA) enzyme." (PMID 34072668, 2021). "Glycogen storage disease type II (GSDII) or Pompe Disease (PD) is a rare autosomal recessive metabolic disorder caused by a deficiency of lysosomal enzyme, acid α-glucosidase (GAA), leading to intracellular glycogen storage in many tissues, mainly in skeletal muscle, heart and liver." (PMID 33228748, 2020). "Pompe disease (PD), a rare autosomal recessive condition also known as glycogen storage disease type II, is caused by a deficiency of the lysosomal enzyme acid alpha-glucosidase (GAA)." (PMID 32373469, 2020). "GSD II, known as Pompe disease, is caused by a defiency in the lysosomal acid-α-glucosidase (GAA)." (PMID 33344388, 2020). "One important member of myopathies is Glycogen storage disease type II (Pompe disease), an autosomal recessive muscle disorder characterized by abnormal glycogen storage due to deficiency of the lysosomal acid alpha-glucosidase (GAA)." (PMID 32823799, 2020). "Pompe disease (PD) is a rare autosomal recessive disorder caused by mutations in the GAA gene, localized on chromosome 17 and encoding for acid alpha-1,4-glucosidase (GAA)." (PMID 32745073, 2020). "Also known as glycogen storage disease type II, Pompe disease is another storage disorder, leading to α-glucosidase (GAA) deficiency and subsequent intralysosomal build-up of glycogen in the affected tissues, including heart, skeletal muscle, and liver." (PMID 31842377, 2019). "Pompe disease is an autosomal recessive disorder caused by deficiency of alpha-glucosidase (GAA)." (PMID 33072949, 2018). "Several studies have reported that use of immunosuppressant drugs, such as cyclophosphamide, mycophenolate mofetil, belimumab, rituximab, bortezomib, and MTX can lead to successful induction of immune tolerance in GAA-deficient mice and in humans with infantile Pompe disease." (PMID 28761815, 2017). "Pompe disease, a rare lysosomal storage disease caused by deficiency of the lysosomal acid α-glucosidase (GAA), is characterized by glycogen accumulation, triggering severe secondary cellular damage and resulting in progressive motor handicap and premature death." (PMID 29061980, 2017). "Glycogen storage disease type II or Pompe disease is an autosomal recessive disorder caused by deficiency of the lysosomal enzyme α–1,4-glucosidase (GAA) leading to accumulation of glycogen resulting in lysosomal dysfunction, autophagy, and progressive tissue damage." (PMID 27931223, 2016). "Pompe disease (glycogen storage disease type II, acid maltase deficiency) (OMIM # 232300) is a rare metabolic myopathy caused by glycogen accumulation resulting from deficiency of lysosomal acid α-glucosidase (GAA)." (PMID 26187632, 2015). "Pompe disease is an autosomal recessive lysosomal glycogen storage disorder that has been reported in different ethnic populations which carry different common mutations of the acid alpha-glucosidase (GAA) gene." (PMID 25526786, 2014). "Glycogen Storage Disease type II (GSDII) or Pompe disease (OMIM 232300) is a lysosomal storage disorder caused by mutations in the acid alpha-glucosidase (GAA) gene whose frequency is about 1 in 40000–50000 in European and US Populations and apparently much lower in Australia or Portugal." (PMID 25103075, 2014). "The reduction in acid α-glucosidase activity, measured in cultured fibroblasts (1.6 nmol/mg/h, normal values 64.4 ± 22.9), and the molecular analysis of the GAA gene that showed a homozygous mutation (C1124G> T/C1124G> T) confirmed the diagnosis of Pompe disease." (PMID 23391190, 2013).
Pompe disease (continued). "As far as we know, this is the largest informative family with late-onset Pompe disease described in the literature showing a peculiar complex set of mutations of GAA gene that may partially elucidate the clinical heterogeneity of this family." (PMID 24107549, 2013). "Pompe disease (also known as glycogen storage disease type II, GSDII) is a rare and severe autosomal recessive disorder caused by a deficiency in the lysosomal enzyme acid α-glucosidase (GAA)." (PMID 41174634, 2025). "Pompe disease, also known as glycogen storage disorder type 2, is an autosomal recessive metabolic disorder caused by an enzymatic deficiency of acid alpha-glucosidase (GAA) in lysosomes, first described by J.C. Pompe, G. Bischoff, and W. Putschar-independently in the year 1932." (PMID 33543425, 2021). "Pompe disease (also known as glycogen storage disease type II, glycogenosis II, or acid maltase deficiency) is a lysosomal storage disorder in which a deficiency in acid α-glucosidase (GAA) causes the intralysosomal accumulation of glycogen in all tissues, most notably skeletal muscles." (PMID 33072961, 2018). "Pompe disease, also known as acid maltase deficiency (AMD) or glycogen storage disease type II (GSDII), is a rare autosomal recessive disorder of glycogen metabolism caused by insufficient activity of the enzyme acid alpha-glucosidase (GAA)." (PMID 26471939, 2015). "Screening tests involve measuring the GAA enzyme levels in peripheral blood, where individuals with Pompe disease typically show very low GAA enzyme activity, less than 1% of normal levels." (PMID 40981304, 2025). "Since 2006, enzyme replacement therapy (ERT) with recombinant human GAA (alglucosidase alfa, Myozyme®) has been the only approved treatment for Pompe disease in Europe and the United States." (PMID 41174634, 2025). "Alglucosidase alfa is a recombinant human GAA (rhGAA) produced in CHO cells that is used as enzyme replacement therapy (ERT) for Pompe disease since 2006." (PMID 40843676, 2025). "For over two decades, enzyme replacement therapy (ERT) with alglucosidase alfa has enabled the treatment of patients with Pompe disease by replacing the missing alpha-glucosidase enzyme through infusions of purified recombinant human alpha-glucosidase (rhGAA)." (PMID 40471681, 2025). "Pompe disease (glycogen storage disease type II, OMIM #232300) is a rare, autosomal recessive metabolic myopathy, caused by pathogenic variants in the GAA gene." (PMID 37982853, 2024). "Pompe disease (PD) or Glycogenosis Type II (GSD II; OMIM #232300) is a rare autosomal recessive lysosomal disorder caused by pathogenic variants in α-glucosidase (GAA)." (PMID 40225932, 2024). "Glycogen storage disease type II (and it is abbreviated as GSD II) is a rare autosomal recessive disorder caused by mutations in the lysosomal endo-acidic alpha-glucosidase (GAA) gene." (PMID 39213226, 2024). "The GAA gene (OMIM *606800) is located on chromosome 17q25 and it is the only gene associated with Pompe disease (OMIM #232300) in the online Mendelian Inheritance in Man Database." (PMID 37759679, 2023). "Gene therapy has been advanced to the initial phase of clinical trials for the replacement of G6P in GSD Ia and acid α-glucosidase (GAA) in GSD II (Pompe disease)." (PMID 37630734, 2023). "Glycogen storage disease type II (GSDII), also named Pompe disease (PD), is an autosomal recessive disorder caused by a deficiency in the acid alpha-glucosidase enzyme (GAA), which is responsible for the hydrolysis of glycogen to glucose in the lysosome." (PMID 37759679, 2023). "In the GAA−/− 129SVE mouse model of Pompe Disease, robust IgG1 antibody generation against human rhGAA is driven by immunodominant CD4+ Th2 cell epitopes, and these affected mice with high IgG antibody titers ultimately die from IgE-mediated anaphylaxis." (PMID 38250073, 2023).
Pompe disease (continued). "Glycogen storage disease type II, also known as Pompe disease (OMIM #232300), is an autosomal recessive neuromuscular disorder caused by deficiency of acid α-glucosidase (GAA), the enzyme hydrolyzing glycogen into glucose within lysosomes." (PMID 37463048, 2023). "Pompe disease, or acid alpha-glucosidase (GAA) deficit, is an autosomal recessive lysosomal storage disease, or glycogen storage disease type II (GSD II), that affects 1 in 40,000 newborns." (PMID 36983602, 2023). "In this study antibody formation and their effect on clinical outcome in patients with childhood onset Pompe disease treated with enzyme replacement therapy (ERT) with recombinant human alpha-glucosidase (rhGAA) are analyzed." (PMID 35109913, 2022). "Pompe disease (OMIM #232300, EC 3.2.1.20) is a GSD that also affects skeletalmuscle; however, in contrast to McArdle disease, the heterozygous mutation inthe GAA gene is within the lysosomes and lysosomal glycogenolysis is blocked." (PMID 37180413, 2022). "Intravenous enzyme replacement therapy (ERT) with recombinant human GAA (rhGAA; alglucosidase alfa), was approved in 2006 for treatment of Pompe disease." (PMID 35813979, 2022). "Pompe disease, or glycogen storage disease type II (GSDII, OMIM 232300), is an autosomal recessive lysosomal storage disorder (LSD) caused by deficiency of the lysosomal enzyme acid-α glucosidase (GAA)." (PMID 36284764, 2022). "All three patients were ascertained through positive NBS for Pompe disease with significantly reduced GAA enzyme activity levels on blood samples." (PMID 36246652, 2022). "Pompe6neo/6neo (also known as Pompe) mice exhibit muscular features typical of patients with Glycogen storage disease type II (GSDII), a recessively inherited deficiency of the enzyme acid α-glucosidase (GAA, acid maltase, EC 3.2.1.20)." (PMID 35351934, 2022). "Pompe disease has been treated by the regular substitution of recombinant GAA enzyme since 2006, which significantly improved survival and reduced the severity of symptoms in patients of both subtypes." (PMID 34072668, 2021). "Pompe disease has been predominantly modeled in the GAA knockout mice that recapitulate key disease features such as striated muscle and nervous tissue glycogen accumulation, lysosomal abnormalities, neuropathology, cardiac defects, and muscle weakness." (PMID 34778273, 2021). "Pompe disease can be treated with systemic recombinant human GAA (rhGAA) enzyme replacement therapy (ERT), but the current standard of care exhibits poor uptake in skeletal muscles, limiting its clinical efficacy." (PMID 33971197, 2021). "Current clinical therapy for Pompe disease is enzyme replacement therapy (ERT) which systemically delivers the recombinant human GAA (rhGAA) to break-down accumulated glycogen." (PMID 34778273, 2021). "Pompe disease, or glycogen storage disease type II (MIM #232300), is a monogenic autosomal recessive disorder caused by deficiency of lysosomal alpha-glucosidase (GAA)." (PMID 34356580, 2021). "Pompe disease, also known as glycogen storage disease type II (GSDII), is a rare metabolic autosomal recessive disorder that results from deficiency of acid α-glucosidase (GAA)." (PMID 34778273, 2021). "Pompe disease (glycogen storage disease type II, OMIM ID: 232300) is an autosomal recessive disorder caused by deficiency of the enzyme acid α-glucosidase (GAA)." (PMID 34362174, 2021). "Newborn screening (NBS) for Pompe disease (PD), utilizes dried blood spots (DBS) to detect deficient alpha-glucosidase (GAA) activity." (PMID 32352041, 2020). "Studies on GAA knockout mice (KO) and the efficacy of enzyme replacement therapy have proved that autophagy defects are a main pathogenesis of Pompe disease." (PMID 32126021, 2020). "To determine the effect of enzyme replacement therapy in the Pompe disease NSCs, we applied recombinant human GAA protein (rhGAA) to these patient-derived cells." (PMID 33375166, 2020).